IL17A (interleukin 17A)
Diseases named in the same sentence as IL17A in open-access papers (continued):
Sharing a sentence is not in itself a finding about the gene and the disease.
depression (continued). "Patients with depression had elevated IL-17A compared to controls (SMD = 0.80 [95% CI 0.03 to 1.58], p = 0.042), an association moderated by antidepressant use (Z = 2.12, p = 0.034)." (PMID 39012496, 2024). "Corroborating data from mouse research attests to the deleterious effects of Th17/IL-17A in depression." (PMID 39655201, 2024). "IL-17A can induce depression-like symptoms through the NF-kB and p38MAPK pathways in mice and hospitalized patients." (PMID 38835777, 2024). "The Beck Depression Inventory Questionnaire data revealed that plasma concentrations of IL-33 and IL-17A were higher in T. gondii-infected pregnant women diagnosed with mild DS." (PMID 38835777, 2024). "Using Beck’s depression inventory, we observed an increase in plasma IL-17A and IL-33 in women with T. gondii infeCction diagnosed with mild DS, whereas neuroserpin was associated with minor and moderate/severe DS." (PMID 38835777, 2024). "Both IL-33 and IL-17A have been identified as potential prognostic markers in human toxoplasmosis and depressive disorders, as evidenced by their high plasma levels in pregnant women with T. gondii infection having mild DS." (PMID 38835777, 2024). "TNF-α on D1, D3, and D7, IL-8 at baseline, D1, D3, and D7, IL-17A on D1 and D7 correlated with increased depression rate (all P<0.05)." (PMID 37878890, 2023). "According to the latest data, in depression, especially the treatment-resistant type, the number of Th17 cells in the blood and the production of IL-17A is increased, which correlates with the severity of the disease." (PMID 38067176, 2023). "In the literature, there is an increasing amount of data confirming the possible role of Th17 lymphocytes and IL-17A in the pathogenesis of depression." (PMID 38067176, 2023). "The discovery that Th17 cells are involved in depression evolves from the classic theory that Th17 cells produce inflammatory cytokines IL-17A and IL-6, which is required for differentiation, and contribute to depression onset and maintenance." (PMID 36911710, 2023). "IL17A/IL-17RA signaling activated by psoriatic inflammation in the brain mediates downstream inflammatory effects required for depression." (PMID 38046578, 2023). "In patients with treatment-resistant depression, higher levels of IL-17A were found in the blood, and pre-treatment level of RORyt mRNA can serve as a biomarker of response to therapy." (PMID 38067176, 2023). "At the same time, anti-IL-17A-antibody reduced depression-like symptoms, as well as NFκB/p38MAPK-signaling." (PMID 36189272, 2022). "Although the etiology of MDD has yet to be determined, mounting evidence supports a link between depression and elevated levels of IL-17A, suggesting that inflammation exacerbates depressive symptoms." (PMID 35935951, 2022). "In this study, this benefit was evidenced by a reduction in airway inflammatory markers, such as IL-4, IL-5, IL-17A, FeNO and lung function, which consequently resulted in better quality of life and decreased depression levels." (PMID 34521963, 2021). "In Ps patients with comorbid depression, high serumconcentrations of IL-6 and IL-18, as well as IL-17A, were presumed to act as sharedinflammatory mechanisms." (PMID 34819201, 2021). "Among the psoriasis patients, anti-IL-17A therapy resulted in remission of depression in about 40% of the patients with severe depression." (PMID 33319101, 2020). "First, we found that the baseline levels of IL-10, IL-12p70, IL-13, IL-17A, IL-1β, IL-2, IL-23, IL-5, IL-6, IL-7, and MIP-1β were associated with depression symptoms." (PMID 32699226, 2020). "Based on the univariate analysis of the GLM, we found significant differences in the years of education, cytokines (IL-1β, IL-2, IL-6, IL-12p70, IL-17A, IFNγ, TNFα, IL-10, and IL-13), and depression severity (indicated by the PHQ) among the groups." (PMID 32703187, 2020).
depression (continued). "Similar thing concerned patients in depression - mean concentration of IL-17A was 28 ± 9,07 vs. 134,15 ± 5,63 (p = 0, 000129, ANOVA with post-hoc Tukey test)." (PMID 30971748, 2019). "The concentration of cytokines (IL-6, TNF-α, IL-17A, IL-10) was measured in the serum of healthy subjects and BD patients in remission or depression." (PMID 30971748, 2019). "Another study on 41 patients with major depressive disorder (MDD) indicated higher concentrations of serum IL-17A in comparison with healthy controls." (PMID 30400354, 2018). "Previously, some other studies have reported correlations between IL-6 and IL-17A and pain and depression, but few of these have used multivariate analyses." (PMID 29849487, 2018). "The IL-23A or IL-17A immunological axis, which is involved in autoimmune and inflammation-related diseases, might also have a function in the development of depression and anxiety disorders." (PMID 38956309, 2024). "During the psoriatic pathological process, whether the increased systemic IL‐17A levels can be responsible for its depression phenomenon by inducing neuronal inflammatory reaction is still a crucial issue to be explored." (PMID 39660880, 2024). "Multiple comparisons showed that neutralization of IL‐17A treatment could significantly alleviate depression levels (p < 0.01 or 0.001), and the performances of IMQ plus neutralization of IL‐17A group were similar to the control group (all p > 0.05)." (PMID 39660880, 2024). "A positive correlation was found for depression with IL-17A on D1 (P=0.041) and D7 (P=0.031)." (PMID 37878890, 2023). "Accordingly, this study intended to explore the association of Th1, Th2, and Th17 cells as well as their corresponding cytokines [including interferon (IFN)-γ, IL-4, and IL-17A] with anxiety, depression, and cognitive impairment in elderly gastric cancer patients." (PMID 36386524, 2022). "Since it is unclear whether CUMS aggravates neuroinflammation through the imbalance between Th17 and Treg, the present study further evaluated the mRNA and protein expression of IL-17A and its receptor IL-17Rc in a model of depression." (PMID 36430328, 2022). "Another possible explanation is that IL-17A expression could vary during disease progression or among depression subtypes." (PMID 33935753, 2021). "Similarly, IL-17A antibody treatment in psoriatic patients with moderate to severe depression resulted in a significant reduction in depressive symptoms in 40% of the patients." (PMID 33935753, 2021). "Furthermore, the anti-IL17A antibody also led to a reduction inimiquimod-induced depression-like symptoms, as well as NFκB/p38 MAPK signaling." (PMID 34819201, 2021). "The present data suggest that it might be worthwhile to see if a relationship exists between IL-17A serum levels and ME/CFS-associated depression." (PMID 34829952, 2021). "IL-17, a pro-inflammatory cytokine, is a member of the cytokine family comprising IL-17A, IL-17B, IL-17C, IL-17D, IL-17E (IL-25) and IL-17F and it was found before, to be elevated in the serum of patients suffering from depression." (PMID 33322667, 2020). "For example, in PsA, depression has been associated with serum IL-6, but not IL-17A or CRP." (PMID 39959848, 2025). "Furthermore, the use of antidepressants to treat depression could decrease the peripheral IL-17A level." (PMID 39358787, 2024). "However, there is evidence that does not support an association between plasma IL-17A, depression, and response to therapy." (PMID 38067176, 2023). "The neutralization of IL-17A by anti-IL-17A antibodies or supplement of serotonin to block the release of gut Th17 cells might represent a reasonable and feasible therapeutic approaches to improve depression symptoms." (PMID 36275694, 2022).
depression (continued). "Therefore, the authors could speculate that the increased IL-17A serum levels in female patients may possibly be explained by that these females could be suffering from psychiatric disorders including depression resulting from their disease state." (PMID 36153175, 2022). "Excessive IL-17A combines with the specific receptor IL-17Rc in microglia and astrocytes, further activates microglia M1 phenotype and astrocyte A1 phenotype and triggers IDO enzyme activity, thereby causing neurotransmitter metabolism and inducing depression-like behaviors." (PMID 36430328, 2022). "However, lack of an association between blood levels of IL-17A and depression has also been reported, as anti-depressants appear not to exert an effect on IL-17 levels." (PMID 34367160, 2021). "Therefore, Th17 cells and IL-17A are considered potential therapeutic targets for depression." (PMID 33935753, 2021). "Peripheral IL-17A immune response may be a preventive and treatment target for depression." (PMID 30400354, 2018). "IL-6 and IL-17A produced by M1-type macrophages cross the BBB and activate M1-type microglia in the brain, which in turn release pro-inflammatory factors to induce depression." (PMID 41301929, 2025). "In discussion of peripheral inflammatory markers and brain reaction or depression, signals of which cytokines cross the BBB should be considered, as mentioned in the IL-17A section above." (PMID 39358787, 2024). "In another fecal transfer experiment, germ-free-like mice that are transferred with the microbiomes of depression patients show increased prevalence of SFB and expression of IL-17A." (PMID 39655201, 2024). "The alarmin IL-33, IL-17A, and the chemokine CCL2 have been highlighted in studies of depressive disorders, and their high production/expression was demonstrated in chronic T. gondii research in both experimental models and humans." (PMID 38835777, 2024). "In the current study, a positive correlation was found between TNF-α, IL-6, IL-8, and IL-17A after AIS onset and anxiety, depression, or cognitive impairment at different time points." (PMID 37878890, 2023). "Meta-analyses and systematic reviews show that levels of IL-1β, IL-2, IL-4, IL-8, the soluble IL-6 receptor (sIL-6R), IL-5, CCL3, IL-17A, and TGF-β1 are significantly changed in depression." (PMID 36614020, 2022). "To prove that IL-17 is involved in the anxiety- and depression-like behavior of CPMS mice, we suppressed the action of IL-17 through anti-IL-17/IL-17A antibody treatment." (PMID 33441182, 2021). "Furthermore, anti-depressant treatment of depression could decrease peripheral IL-17A levels." (PMID 30400354, 2018). "Correlation analysis shows that Th17 cells and IL-17A levels are not always correlated with the intensity and duration of depressive symptoms in children, adolescents, and late-life depression." (PMID 39655201, 2024). "For instance, TNF‐α, IL‐1β, IL‐6, and IL‐17A are elevated in coronary heart disease patients with anxiety and depression in comparison to those without these disorders." (PMID 37878890, 2023). "This fits our hypothesis that increased IL-17A and IL-6/TGF-β might contribute to depression-like behaviors." (PMID 36430328, 2022). "In contrast, splenic T-lymphocyte expression of IL-6 or IL-17A did not correlate with anxiety-like behavior indices but IL-6 positively correlated with depression-like behavior indices, which has been previously reported." (PMID 31139062, 2019). "Interestingly, in late-life depression, IL-17A levels do not correlate with the severity of depressive symptoms but correlate with cognitive assessments." (PMID 38067176, 2023). "There are also data which show that IL-17A levels do not always correlate with depression." (PMID 33498653, 2021).
depression (continued). "The downregulation of HDC expression led to the activation of the IL-6/STAT3/S100A9 pathway, stimulating Th17 cells to secrete IL-17A, thereby promoting ovarian cancer progression, which suggests that HDC may be a potential therapeutic target for the comorbidity of ovarian cancer and depression." (PMID 39720595, 2024). "When compared with participants without depression or subsequent cognitive decline, patients with LLD were shown to have elevated concentrations of CCL-2 and CCL-4 and cytokines IL-17a, IL-33, IFN-γ and IL-1ra, as well as IL-33 in most models." (PMID 39922907, 2025).
Stroke (163 papers, 2013 to 2025). Sudden impairment of blood flow to a part of the brain due to occlusion or rupture of an artery to the brain. "Clinically, the concentrations of Th17 cells and IL-17A in peripheral blood are associated with stroke severity and serve as predictors of neuropsychiatric complications." (PMID 41357230, 2025). "Several studies have shown that Th17 cells and IL-17A are present in high numbers in the peripheral blood of patients with IS and are positively associated with severity, poor prognosis, and stroke sequelae such as cognitive impairment." (PMID 37884768, 2024). "furthermore, the worse stroke outcome was abolished in the IL-17A knockout mice, suggesting that increased IL-17A is associated with exacerbation of AIS." (PMID 38817358, 2024). "The promoting effect of IL-17A on angiogenesis was associated with the expression of IL-6 during the stroke recovery stage." (PMID 36873773, 2023). "Neutralization of IL-17A following stroke reversed the worse outcome in IL-10 deficient mice and intracerebral treatment with recombinant IL-10 revealed that IL-10 controlled IL-17A positive lymphocytes in ischemic brains." (PMID 34772416, 2021). "For instance, the elevated levels of IL-17A following a stroke are associated with reduced IL-10, and the suppression of IL-17A may enhance the outcomes in mice lacking IL-10." (PMID 39881806, 2024). "In this study, our results showed that astrocytic IL-17A promoting post-stroke angiogenesis in enriched animals might be linked with the upregulation of IL-6, JAK2, and STAT3, and moreover, that this promoting effect was neutralized by anti-IL-17 mAb." (PMID 36873773, 2023). "Likewise, IL-17a and γδ T cells have also been demonstrated to be implicated in human stroke." (PMID 35432162, 2022). "Importantly, in these studies, the expression of IL-17A was maximal in human carotid artery plaques derived from symptomatic patients with stroke or transient ischemic attack, a piece of evidence that fits well with the concept that IL-17A is associated with plaque instability." (PMID 32010143, 2019). "γδT cells produce the majority of IL-17A in the acute phase (3 days following stroke), while the majority of IL-17A in the chronic phase (28 days later) is produced by astrocytes, and have different roles in recovery at different temporal stages." (PMID 39103660, 2025). "Specifically, γδ T cells typically exacerbate acute brain injury through IL-17A production, triggering a highly conserved innate immune response in the acute phase of stroke." (PMID 40746532, 2025). "Taken together, these results suggest that LIPUS promotes the differentiation of OPCs and improves the integrity of cerebral WM after stroke mainly through IL-17A/Notch1 signaling." (PMID 40290135, 2025). "Some studies have demonstrated that IL-17A secreted by gamma delta T cells serves as a crucial source in stroke pathogenesis." (PMID 40948793, 2025). "Specifically, the γδ17 T cell subset rapidly infiltrates the brain during the early phase of stroke and releases IL-17A, thereby amplifying detrimental immune responses and exacerbating brain injury." (PMID 40746532, 2025). "Studies demonstrate that blocking γδ T cells, IL-17a, or IL-21 confers significant neuroprotective effects against ischemic brain injury in murine stroke models, establishing them as promising therapeutic targets for mitigating ischemic brain damage." (PMID 40746532, 2025). "During acute phases of stroke, IL-17A is involved in microglial activation and neuroinflammation, promoting the expression of TNF-α, IL-1β, and other inflammatory factors and downstream signaling molecule NF-κB p65." (PMID 40289984, 2025). "This elevation of astrocytic IL-17A supports spontaneous recovery after stroke and promotes synaptogenesis." (PMID 39103660, 2025).
Stroke (continued). "Patients with ischemic stroke exhibit elevated levels of Th17 cells and IL-17A in their peripheral blood, which correlate positively with disease severity, poor prognosis, and post-stroke complications." (PMID 40948793, 2025). "The administration of IL-17A neutralizing antibodies and IL-17A knockout decreased the severity of stroke-induced brain injury." (PMID 40948793, 2025). "A study found that peripheral cytokines, including IL-17A, had little predictive value for the recovery of cognitive function during inpatient rehabilitation after stroke." (PMID 41291751, 2025). "A growing number of studies have shown that IL-17A acts on multiple resident cells in the central nervous system, enhancing the neuroinflammatory response after stroke and exacerbating ischemic brain injury." (PMID 37884768, 2024). "Th17 cells and IL-17A have prominent pleiotropic properties in regulating pro- and anti-inflammatory responses after stroke." (PMID 37884768, 2024). "Studies have shown that Th17 cells and IL-17A correlate with VCI after stroke and that the proportion of Th17 and IL-17 levels in IS patients at admission are positively associated with cognitive decline 1 and 2 years after IS." (PMID 37884768, 2024). "We review the function of Th17/IL-17A, the mechanism of action of Th17/IL-17A in stroke, and Th17/IL-17A-related stroke therapy." (PMID 37884768, 2024). "Intestinal epithelial stem cell (Lgr5 + stem cells) transplantation reduced circulating levels of LPS and IL-17A and improved cognitive function 4 weeks after stroke by repairing the intestinal structure and decreasing intestinal permeability." (PMID 37884768, 2024). "Infiltrating intrinsic immune cells, γδ T cells, are the primary source of IL-17A for 12 h to 3 days after stroke." (PMID 37884768, 2024). "EE rats treated with anti-IL-17A antibodies exhibited significantly reduced protein expression of CD34 in penumbra at 21 days after stroke compared with those in the EE and EE + isotype groups (P < 0.01)." (PMID 36873773, 2023). "In the murine stroke model, neutralization of interleukin-17A resulted in a significant reduction of infarct sizes three days after ischaemia." (PMID 37056478, 2023). "IL-17A was found to be mainly derived from astrocytes and to augment neurogenesis and functional recovery after stroke." (PMID 36873773, 2023). "In this study, our data provide evidence that EE treatment promoted angiogenesis by increasing the protein expression of VEGF and CD34 in the ischemic penumbra through astrocytic IL-17A during the recovery phase after stroke." (PMID 36873773, 2023). "Then, we analyzed the outcome of stroke and change of immune cells in the brain and gut, and revealed significant alterations of IL-17A-producing cells." (PMID 35663549, 2022). "We identified IL-1 as a potent activator of IL-17A production in γδ T cells in the acute phase following stroke." (PMID 35384588, 2022). "Absolute numbers of IL-17A+ γδ T cells 72 h post-stroke were also significantly reduced in the ischemic hemisphere of Il1−/− mice and the typical increase in IL-17A+ γδ T cells from 24 to 72 h post-stroke was abrogated in Il1−/− mice." (PMID 35384588, 2022). "A possible role of inhibitory PD-1 signaling to control IL-17A+ γδ T cells in stroke is supported by our data showing an increased frequency of PD-1+ IL-17A+ γδ T cells in the ischemic brain when compared to cervical lymph nodes." (PMID 34772416, 2021). "IL-17A is seen as a decisive factor for the early detrimental postischemic inflammatory response following stroke." (PMID 34772416, 2021). "Taken together, our data indicate a key function of IL-10 in restricting the detrimental IL-17A-signaling in stroke and further supports that IL-17A is a therapeutic opportunity for stroke treatment." (PMID 34772416, 2021).